SPP1 (secreted phosphoprotein 1)
Diseases named in the same sentence as SPP1 in open-access papers (continued):
Sharing a sentence is not in itself a finding about the gene and the disease.
cyst (4 papers, 2019 to 2025). A sac-like closed membranous structure that may be empty or contain fluid or amorphous material. "We also analysed the distance of SPP1+ CD31+ blood vessels relative to the nearest neighbouring cyst epithelial boundary." (PMID 40114603, 2025). "Upon 3D imaging of optically cleared ADPKD tissue, we observed networks of CD31+ blood vasculature near SPP1+ cyst-lining cells." (PMID 40114603, 2025). "Kidney histology revealed a reduced cyst burden in pcy/pcy; Spp1−/− compared to pcy/pcy; Spp1+/+ mice." (PMID 39238069, 2024). "Despite a reduction in cyst burden, pcy/pcy; Spp1−/− kidneys exhibited increased expression of genes involved in kidney fibrosis, including α‐smooth muscle actin (Acta2), collagen 1 α1‐subunit (Col1α1), and transforming growth factor‐β (TGFβ)." (PMID 39238069, 2024). "In addition, we found that the SPP1/CD44 interaction pair stood out among the immune–cyst cell interaction pairs; i.e., macrophages and T lymphocytes specifically highly express CD44, which interacts with osteopontin (OPN) encoded by the SPP1 gene expressed by cyst cells." (PMID 37583898, 2023). "Across n=3 Pkd1RC/RC mice and 40 individual SPP1+ CD31+ vessels, we found 60% (24 out of 40) of the SPP1+ vessels to be within 100 μm from the nearest cyst boundary, whereas the remaining 40% (16 out of 40) were greater than 100 μm away from cysts." (PMID 40114603, 2025). "Interestingly, despite an obvious decrease in cyst burden in pcy/pcy lacking Spp1, our observation of slightly higher BUN and serum creatinine measurements suggested worse kidney function in this group." (PMID 39238069, 2024). "In addition to FGFR2/FGF9, we also found that SPP1/CD44 interactions between immune cells, especially macrophages, and cyst cells may play an important role in the induction of cyst cell formation." (PMID 37583898, 2023).
dermatomyositis (4 papers, 2008 to 2025). Dermatomyositis (DM) is a type of idiopathic inflammatory myopathy characterized by evocative skin lesions and symmetrical proximal muscle weakness. "In dermatomyositis-associated ILD (DM-ILD), serum SPP1 levels correlate with disease severity, especially in patients with anti-MDA5 antibodies, who are at higher risk of developing rapidly progressive ILD." (PMID 40559389, 2025).
encephalitis (4 papers, 2017 to 2020). An acute inflammatory process affecting the brain parenchyma. "Osteopontin (Opn), or secreted phosphoprotein 1 (SPP1), is a cytokine-like glycophosphoprotein found elevated in brain samples collected post-mortem from HIV infected subjects with neurocognitive impairments or encephalitis." (PMID 32512754, 2020).
infertile (4 papers, 2013 to 2025). "Increased SPP1 in our gestational adenomyosis organoids compared with control suggests abnormal endometrial SPP1 expression during implantation window and placentation and could contribute to adenomyosis-related infertility." (PMID 35207707, 2022).
lung squamous cell carcinoma (4 papers, 2022 to 2024). "SPP1+ macrophages were significantly increased in the tumor microenvironment, which was related to the poor prognosis of patients with lung squamous cell carcinoma." (PMID 38347955, 2023). "In lung squamous cell carcinoma, there also existed subpopulation of SPP1+TAMs." (PMID 38347955, 2023). "Furthermore, the overexpression of SPP1 was substantially associated with clinicopathological features and unfavorable survival outcomes in individuals with LUAD, whereas no such correlation was observed in lung squamous cell carcinoma." (PMID 38329443, 2024).
malignant glioma (4 papers, 2015 to 2024). A grade III or grade IV glioma arising from the central nervous system. "Several studies have implicated SPP1 with crucial roles in invasion and malignant gliomas." (PMID 31414377, 2019). "NRF2 has been shown to interact with SPP1 in human malignant glioma and Nrf2−/− lung tumors." (PMID 31884422, 2019). "Furthermore, we identified GAMs as the predominant source for the pro-tumorigenic proteins GPNMB and SPP1 in murine and human malignant glioma – highlighting the importance of macrophages and microglia as therapeutic targets in anti-tumor treatment regimens." (PMID 25658639, 2015). "Moreover, both stRNA-seq and scRNA-seq indicated that BRMS1 + microglia may promote the proliferation and invasion of malignant glioma cells through SPP1/CD44-mediated intercellular interactions." (PMID 39143438, 2024).
malignant mesothelioma (4 papers, 2011 to 2025). A malignant neoplasm of the pleura or peritoneum, arising from mesothelial cells. "Malignant mesothelioma cells were screened for the expression of markers associated with the osteoblast cell lineage; RUNX2, SPARC and SPP1." (PMID 27886205, 2016).
penile cancer (4 papers, 2023 to 2025). A primary or metastatic malignant neoplasm that affects the penis. "Enzyme-linked immunosorbent assay (ELISA) method was adopted to detect SPP1 level in the serum of 60 patients with penile cancer." (PMID 38111044, 2023). "We used immunohistochemistry to detect the expression of SPP1 protein and immune cell related proteins in penile cancer tissue." (PMID 38111044, 2023). "Differential analysis indicated that SPP1 was the most differentially upregulated gene in both penile cancer tissues and positive lymph node tissues." (PMID 38111044, 2023). "Then, we performed weighted gene coexpression network analysis (WGCNA) to identify the genes related to SPP1 in penile cancer tissue and positive lymph node tissue." (PMID 38111044, 2023). "ELISA demonstrated that the serum level of SPP1 in patients with positive lymph node metastasis of penile cancer was significantly higher than that in patients with negative lymph node metastasis of penile cancer." (PMID 38111044, 2023).
sarcopenia (4 papers, 2016 to 2026). Progressive decline in muscle mass due to aging which results in decreased functional capacity of muscles. "Thus, Spp1 and S100a9 are associated with the molecular phenotypes of sarcopenia." (PMID 39911133, 2025). "Through multiomics analysis, cellular evaluation and animal experiments, Spp1 may be a promising target for treating CKD with sarcopenia." (PMID 39911133, 2025). "Employing multiomics analysis, cellular assessment and animal experiments, we have identified that Spp1 could potentialy serve as a promising therapeutic target for CKD patients with sarcopenia." (PMID 39911133, 2025). "However, the relationship between Spp1, the ECM and sarcopenia requires further investigation." (PMID 39911133, 2025).
silicosis (4 papers, 2016 to 2025). Silicosis is a respiratory disease caused by breathing in (inhaling) silica dust. "SPP1 is implicated in the pathogenesis of both silicosis and asbestosis, contributing to chronic inflammation and fibrotic remodeling." (PMID 40559389, 2025). "One mechanism by which SPP1 contributes to silicosis involves the release of macrophage-derived exosomes." (PMID 40559389, 2025). "Several osteoclast marker genes were significantly increased in the AMs of silicosis lungs compared to baseline including Ctsk, Spp1, and Atp6v0d2." (PMID 38985878, 2024). "SPP1 expression is also elevated in the lungs of patients with silicosis." (PMID 40559389, 2025). "The Fibr-2 macrophage subset likely represents end-stage profibrotic macrophages in the silicosis lung due to waning expression of profibrotic genes coupled with increased expression of foamy macrophage markers including Spp1, Cd36, and lipid-metabolizing genes such as Lgals3 and Lrp1." (PMID 38985878, 2024).
subarachnoid hemorrhage (4 papers, 2019 to 2025). A serious neurological disorder characterized by intracranial hemorrhage into the subarachnoid space. "Research has demonstrated that Spp1 is involved in activating anti‐inflammatory microglia following subarachnoid hemorrhage, leading to reduced inflammation." (PMID 39939834, 2025).
ulcerative colitis (4 papers, 2011 to 2024). An inflammatory bowel disease involving the mucosal surface of the large intestine and rectum. "Furthermore, only C1q+ Mph could be identified in the colon mucosa of ulcerative colitis patients and healthy individuals, whereas SPP1+ Mph were largely absent in non-cancer tissues, suggesting a unique function in the CRC tumor environment." (PMID 38500875, 2024).
uveal melanoma (4 papers, 2017 to 2025). A melanoma derived from melanocytes of the uveal tract. "Analysis of single-cell RNA-seq data from uveal melanoma patients indicated elevated expression of SPP1 in pro-angiogenic macrophages and inflammatory and antigen-presenting CAFs." (PMID 40362553, 2025).
acne (3 papers, 2019 to 2023). An inflammatory process of the sebaceous glands which is characterized by comedones, nodules, papules and/or pustules on the skin. "Further investigations could provide detailed insights into the role of SPP1+ macrophages in acne pathogenesis including scar formation." (PMID 34746181, 2021). "However, the roles of TNC and SPP1 in acne have not been reported until now." (PMID 31281837, 2019).
adenomyosis (3 papers, 2020 to 2022). The growth of endometrial tissue inside the muscular wall of the uterine corpus. "SPP1, which is involved in endometrial-embryo signaling and embryo attachment, was upregulated in adenomyosis secretory organoids compared with healthy organoids, as it was described in adenomyosis women ectopic endometrium." (PMID 35207707, 2022). "Adenomyosis organoids showed higher expression of TGF-β2 and SMAD3 and increased gene expression of SPP1, PAEP, LIF, and 17βHSD2 compared with control organoids." (PMID 35207707, 2022). "SPP1, PAEP, LIF, and 17βHSD2 expression were upregulated in adenomyosis sec- and gest-organoids compared with control organoids, indicating possible molecular mechanisms involved in adenomyosis-impaired implantation and pregnancy disorders." (PMID 35207707, 2022).
allergic contact dermatitis (3 papers, 2012 to 2025). An inflammatory skin condition caused by an immune response to direct contact between the skin and an allergen. "High OPN levels have also been linked to increased pathogenesis in several autoimmune disorders such as Allergic Contact Dermatitis (ACD), which may also be exacerbated by potential multiple variants of SPP1 that arise due to differential splicing effects." (PMID 39857756, 2025). "SPP1 has roles in the migration and recruitment of neutrophils and has been implicated in the development of allergic contact dermatitis - as such it may also play an important role in sheep scab pathogenesis." (PMID 22880105, 2012).
angiosarcoma (3 papers, 2024 to 2025). A malignant tumor arising from the endothelial cells of the blood vessels. "This study demonstrated that SPP1 overexpression is significantly associated with chemoresistance and poorer survival outcomes in human angiosarcoma (AS)." (PMID 39409192, 2024). "Hence, transcriptome analysis may elucidate molecular mechanisms underlying chemoresistance, as well as the role of SPP1 in angiosarcoma, aiding in the identification of novel biomarkers for targeted therapies for angiosarcoma." (PMID 39409192, 2024). "We examined SPP1 expression in the angiosarcoma tumor archival FFPE samples using immunohistochemistry." (PMID 39409192, 2024). "Nevertheless, we have presented preliminary evidence supporting SPP1 as an indicator of chemoresistance in angiosarcoma and investigated its potential clinical significance." (PMID 39409192, 2024). "In this study, we examined SPP1 expression in angiosarcoma and its role in chemoresistance using NanoString gene expression data, immunohistochemistry, and in vitro testing." (PMID 39409192, 2024). "In conclusion, this study illustrates SPP1 overexpression in AS and its potential role as both a predictive biomarker of chemoresistance and a prognostic biomarker in angiosarcoma." (PMID 39409192, 2024). "SPP1 expression was present across all cell types in angiosarcoma, including stromal, immune, and tumor cells, and in corroboration with NanoString immune profiling, was most enriched in myeloid cells." (PMID 39409192, 2024). "In conclusion, SPP1 overexpression may be a biomarker of chemoresistance and poor prognosis in angiosarcoma." (PMID 39409192, 2024). "Finally, using mIHC staining, we demonstrated that OLR1 + and SPP1 + macrophages were increased in angiosarcoma tissues." (PMID 39658531, 2024). "Immunohistochemistry showed a significant moderate positive correlation between SPP1 protein and gene expression (r = 0.7016; p < 0.00110), while higher SPP1 protein expression correlated with lower chemotherapeutic sensitivity in patient-derived angiosarcoma cell lines MOLAS and ISOHAS." (PMID 39409192, 2024).
aortic stenosis (3 papers, 2016 to 2022). Aortic valve stenosis is a aortic valve disease caused by the incomplete opening of the aortic valve. "In previous bioinformatic research on 6 valvular tissue samples from patients with aortic stenosis, RNA-Seq analysis suggested that SPP1 was significantly up-regulated in aortic valve sclerosis." (PMID 34020624, 2021).
aortic valve stenosis (3 papers, 2024 to 2025). Aortic valve stenosis (AVS) is a condition characterized by narrowing of the heart's aortic valve opening. "H&E staining, the inflammation scores, Masson staining, fiber score, PAS staining, and PAS score showed less inflammatory infiltration, tracheal stenosis, fibrosis, and mucus formation in Spp1−/−+OVA+FMT group mice compared with Spp1−/−+OVA mice." (PMID 40401951, 2025).
B cell lymphomas (3 papers, 2012 to 2025). "Here, we investigated the regulation and function of aberrantly expressed signalling factor SPP1 in HL by both analyzing patient datasets from different types of B-cell lymphoma and by exploiting HL cell lines as experimental models." (PMID 40149711, 2025). "Thus, SPP1 is aberrantly expressed in subsets of particular B-cell lymphomas, including HL, DLBCL and MCL." (PMID 40149711, 2025). "In addition, we detected SPP1 overexpression in 1/11 (9.1%) DLBCL patients, and in 1/22 (4.5%) MCL patients, showing that SPP1 upregulation plays a role in subsets of selected B-cell lymphomas." (PMID 40149711, 2025). "Expression analyses of SPP1 in normal and malignant cells and tissues showed that SPP1 is absent in developing and mature B-cells but is aberrantly activated in subsets of selected B-cell lymphomas, including HL, DLBCL and MCL." (PMID 40149711, 2025). "Taken together, aberrantly expressed SPP1 was detected in subsets of HL patients and the HL cell line SUP-HD1, endorsing its choice as a model to investigate the regulation and function of SPP1 in this type of B-cell lymphoma." (PMID 40149711, 2025).
Chronic colitis (3 papers, 2017 to 2022). A chronic inflammatory disease of the large intestine (colon, cecum and rectum). "Finally, adoptive transfer of naïve CD62LhiCD4+ T cells into Rag-2-/-Spp-1-/- mice resulted in less chronic colitis than Rag-2-/- recipient mice." (PMID 31291255, 2019).
coronary stenosis (3 papers, 2016 to 2024). Narrowing of the coronary artery lumen diameter. "Strikingly, correlation analyses uncovered that higher level of SPP1 in PVAT correlates with a more severe fibrosis degree and a higher coronary stenosis grade." (PMID 37706320, 2023). "Importantly, the mRNA level of SPP1 in coronary PVAT was positively related to the fibrosis degree of coronary PVAT, as well as coronary stenosis grade." (PMID 37706320, 2023).
esophageal adenocarcinoma (3 papers, 2019 to 2025). A malignant tumor with glandular differentiation arising predominantly from Barrett mucosa in the lower third of the esophagus. "They observed significantly higher SPP1 levels in EAC patients compared to those with Barrett’s esophagus and low-grade dysplasia." (PMID 41391064, 2025).
fungal infection (3 papers, 2010 to 2025). "We differentiated macrophages with each cytokine, then exposed them to Coccidioides in vitro to determine which cells would respond to fungal infection by upregulation of Spp1." (PMID 40704794, 2025).
gastrointestinal stromal tumor (3 papers, 2011 to 2021). "However, it was recently shown that the hypo-methylation of a CpG dinucleotide 647 base pair upstream of the transcription start site of SPP1 was associated with shorter disease free survival in gastrointestinal stromal tumors (GIST)." (PMID 34359694, 2021).
gout (3 papers, 2018 to 2023). A condition characterized by painful swelling of the joints, which is caused by deposition of urate crystals. "Interestingly, ABCG2, PKD2, and SPP1 genes were found to be significantly related to gout/AH in all three comparisons (gout vs normal; gout vs AH; AH vs normal)." (PMID 36221101, 2022).
Graves disease (3 papers, 2013 to 2021). Graves' disease is an autoimmune disorder that leads to overactivity of the thyroid gland (hyperthyroidism).It is caused by an abnormal immune system response that causes the thyroid gland to produce too much thyroid hormones. "It was demonstrated that SPP1 levels were increased in the serum of patients suffering from Graves’ disease." (PMID 32500465, 2020).
Hodgkins lymphoma (3 papers, 2014 to 2025). A heterogeneous group of malignant lymphoid neoplasms of B-cell origin characterized histologically by the presence of Hodgkin and Reed-Sternberg (HRS) cells in the vast majority of cases. "The primary objective of this study was to investigate the potential role of tissue osteopontin, also known as secreted phosphoprotein 1 (SPP1), as a contributing factor to an unfavorable prognosis in classical Hodgkin’s lymphoma (HL) patients who received the same treatment protocol." (PMID 38275392, 2023).
Hypercholesterolemia (3 papers, 2016 to 2025). An increased concentration of cholesterol in the blood. "In response to d-flow under hypercholesterolemia, all MΦ clusters significantly accumulated, most notably MΦ3 and MΦ4 that highly expressed the markers of foam cells (Trem2, Lgals3, Gpnmb, Spp1, Lpl, and Fabp5)." (PMID 40092444, 2025).
hypothyroidism (3 papers, 2016 to 2021). Abnormally low levels of thyroid hormone. "The top five hub genes associated with hypothyroidism are ALB, MAPK1, SPP1, PPARG, and MIF, whereas those associated with hyperthyroidism are ALB, FCGR2B, CD44, LCN2, and CD74." (PMID 32500465, 2020). "After PPI network construction, the top five hub genes associated with hypothyroidism were extracted, including ALB, MAPK1, SPP1, PPARG, and MIF, whereas those associated with hyperthyroidism were ALB, FCGR2B, CD44, LCN2, and CD74." (PMID 32500465, 2020).
idiopathic interstitial pneumonia (3 papers, 2009 to 2025). A class of diffuse lung diseases that typically affect the pulmonary interstitium, although some also have a component affecting the airways (for instance, Cryptogenic organizing pneumonitis). "Plasma SPP1 levels—either alone or in combination with surfactant protein-D (SP-D) and MMP-7—have been shown to differentiate IPF from other idiopathic interstitial pneumonias (IIPs)." (PMID 40559389, 2025). "Interestingly, SPP1 have been localized to the alveolar epithelial cells in IPF lungs, was also significantly elevated in bronchoalveolar lavage fluid from IPF patients and, has been detected in plasma from patients with idiopathic interstitial pneumonia." (PMID 19347046, 2009).
IgA nephropathy (3 papers, 2022 to 2025). "SPP1 was also observed to have 10 exons significantly different in IgA nephropathy-affected samples from RCC tissue in the dataset GSE141295 compared to normal cortex samples." (PMID 39857756, 2025).
intestinal tumor (3 papers, 2017 to 2023). "SPP1 is a Wnt/β-catenin target gene and administration of the COX-2 inhibitor parecoxib to APC∆14/+ mice, which display a FAP phenotype, downregulates SPP1 by inhibition of Wnt/β-catenin while decreasing intestinal tumor load and mice morality." (PMID 31211760, 2019).